ACTC1 (actin alpha cardiac muscle 1)
Description:
Actins are highly conserved proteins that are involved in various types of cell motility and are ubiquitously expressed in all eukaryotic cells.
Synonyms: ACTC; CMD1R; ASD5; CMH11; LVNC4
Tractability: Small molecule: a structure with a bound ligand is known. PROTAC: ubiquitination databases record sites on it.
Target class: Enzyme; Hydrolase
Gene: Protein-coding gene on chromosome 15 (34,790,107 to 34,795,912, reverse strand). Ensembl gene ENSG00000159251.
Subcellular location: Cytoplasm, cytoskeleton
Pathways (Reactome):
Cell-Cell communication: Activation of STAT3 by cadherin engagement; Regulation of CDH1 Function
Signal Transduction: RHOA GTPase cycle; RHOB GTPase cycle
Extracellular matrix organization: Formation of the dystrophin-glycoprotein complex (DGC)
Muscle contraction: Striated Muscle Contraction
Gene Ontology:
Molecular function: ATP binding; microfilament motor activity; myosin binding; protein binding; ATP hydrolysis activity; structural constituent of cytoskeleton
Biological process: actin filament-based movement; actin-myosin filament sliding; heart contraction; actin filament organization; actomyosin structure organization; cardiac muscle tissue morphogenesis; cardiac myofibril assembly; mesenchyme migration; positive regulation of gene expression; skeletal muscle thin filament assembly
Cellular component: actin filament; blood microparticle; cytoplasm; extracellular exosome; extracellular region; focal adhesion; membrane; sarcomere; actin cytoskeleton; cell body; cytosol; filopodium; I band; lamellipodium; cytoskeleton; glutamatergic synapse; synapse
Genetic constraint (gnomAD): Loss-of-function variants: 10 observed, 33.16 expected, observed/expected ratio (o/e) 0.3, 90% interval 0.19 to 0.51. The upper end of that interval is the gene's LOEUF score, 0.51, which puts it in group 2 of 6, group 1 being the genes least tolerant of losing a copy. Missense variants: 129 observed, 526.1 expected, observed/expected ratio (o/e) 0.25, 90% interval 0.21 to 0.28. Synonymous variants: 196 observed, 195.86 expected, observed/expected ratio (o/e) 1, 90% interval 0.89 to 1.13.
Gene-disease validity (ClinGen):
ClinGen rates the evidence that ACTC1 causes each of these diseases.
hypertrophic cardiomyopathy (autosomal dominant): Definitive. A condition in which the myocardium is hypertrophied without an obvious cause.
dilated cardiomyopathy 1R (autosomal dominant): Moderate.
arrhythmogenic right ventricular cardiomyopathy (autosomal dominant): No Known Disease Relationship.
Homologues: Orthologues: chimpanzee ACTC1 (100% identical), dog ACTC1 (100% identical), guinea pig ACTC1 (100% identical), macaque ACTC1 (100% identical), mouse Actc1 (100% identical), pig ACTC1 (100% identical), rabbit ACTC1 (100% identical), rat Actc1 (100% identical), tropical clawed frog actc1 (100% identical), zebrafish actc2 (99% identical). Paralogues in human: ACTA1 (99% identical), ACTG2 (99% identical), ACTA2 (98% identical), ACTB (94% identical), ACTG1 (93% identical), ACTBL2 (88% identical), ACTR1B (54% identical), ACTR1A (53% identical), ACTRT3 (49% identical), ACTR2 (48% identical), ACTRT2 (47% identical), ACTRT1 (47% identical), and 14 more.
Diseases named in the same sentence as ACTC1 in open-access papers:
ACTC1 is named in the same sentence as 83 diseases in open-access papers, as found by Europe PMC text mining. Sharing a sentence is not in itself a finding about the gene and the disease. The quoted sentences say what the papers report.
cardiomyopathies (25 papers, 2008 to 2025). "A total of 18 gene records were retrieved for heart disease, the most common gene being ACTC1, which has been documented to cause cardiomyopathies." (PMID 37195695, 2023). "Depending on the domain, ACTC1 mutation can lead rather to congenital heart defects or to cardiomyopathies." (PMID 26061005, 2015). "ACTC1, an autosomal dominant variant, is associated with hypertrophic and other cardiomyopathies." (PMID 41287789, 2025). "We identified five unrelated families in which a total of eight individuals have heterozygous, rare, pathogenic variants in ACTC1 and share similar phenotypic effects, including multiple congenital contractures, neck pterygia, scoliosis, and congenital heart defects/cardiomyopathy." (PMID 37457373, 2023). "Interestingly, protein and mRNA levels of MYH7, MYL3, and ACTC1, the major sarcomere genes whose variants can cause inherited cardiomyopathies such as HCM, and dilated cardiomyopathy were significantly increased in SCH cases." (PMID 37284852, 2023). "We identified 250 down-regulated genes, with many of them known to be important for heart development, such as Ttn, Cav1, Bmp5, and Actc1; Go Ontology (GO) analysis showed that these genes are important for maintaining normal heart function or are closely implicated in cardiomyopathies." (PMID 31541101, 2019). "ACTC1 has previously been associated with various forms of cardiomyopathies." (PMID 31680804, 2019). "The aim of this study was to functionally test five intronic variants (MYBPC3-c.506-2A>C, MYBPC3-c.906-7G>T, MYBPC3-c.2308+3G>C, SCN5A-c.393-5C>A, and ACTC1-c.617-7T>C) found in five patients affected by inherited cardiomyopathies in the attempt to verify their pathogenic role." (PMID 27834932, 2016). "In April 2024, the ClinGen Cardiomyopathy Variant Curation Expert Panel (VCEP) adapted the ACMG/AMP criteria for eight of the sarcomeric genes (MYH7, MYBPC3, TNNI3, TNNT2, TPM1, ACTC1, MYL2, and MYL3), providing a refined framework for variant interpretation in these genes." (PMID 41357762, 2025). "Previously reported pathogenic ACTC1 variants only affect cardiac muscle (e.g., atrial septal defect or cardiomyopathy), and variants in other genes underlying DA have not been associated with cardiac abnormalities." (PMID 37457373, 2023). "In addition to LMNA, mutations to CAV3, ACTA1, ACTC1, DYSF, and DSG2 are linked to cardiomyopathies and encode proteins that are long-lived in the heart." (PMID 37162946, 2023). "Besides the hub genes of MYBPC3, MYH7, and DSP, these subnetworks also include several genes that have been implicated in cardiomyopathy, such as TPM1, ACTC1, DES, TCAP, JUP, and DSG2." (PMID 32344918, 2020). "Beyond residue Met178, all reported ACTC1 mutations result in diverse cardiomyopathies with an unusual prevalence of non-compaction of the apex or hypertrophied apex." (PMID 26061005, 2015). "Recent evidence suggests that genetic defects in the ACTC1 gene are associated with IDC (idiopathic dilated cardiomyopathy), FHC (familial hypertrophic cardiomyopathy), and ASD and that additional mutations in ACTC1 gene might implicated in such type of cardiomyopathy." (PMID 36011517, 2022). "Several proteins involved in heart failure were downregulated, which were found with the terms “Dilated cardiomyopathy” and “Cardiac muscle contraction”, such as TPM1 (Tropomyosin 1), TNNT2 (Troponin T2), ACTC1 (Actin, alpha, cardiac muscle 1)." (PMID 32165613, 2020). "A few lncRNAs are located in the introns of cardiomyopathy-related genes (e.g., TTN, ACTC1, TPM1, JPH2, ANKRD1, DTNA, TMPO, and FHL2) or physically close to these genes." (PMID 32344918, 2020). "A significantly decreased level of ACTC1 (4.9-fold) in FRDA patients is seen in this study, which correlates with the observed mild cardiomyopathy and T wave inversion observed in around 20% patients." (PMID 31680804, 2019).
cardiomyopathies (continued). "Thus, mutations in TBX20, MYH7, NKX2-5, GATA4, and ACTC1 lead to a variety of cardiac anomalies including CHD, arrhythmia and cardiomyopathies." (PMID 26061005, 2015). "Median ACTC1 protein levels were 64 % lower in the myocardium of CCC patients than in myocardial samples from individuals without cardiomyopathies (p<0.001)." (PMID 24367596, 2013).
hypertrophic cardiomyopathy (18 papers, 2014 to 2025). "ACTC1 is responsible for encoding cardiac actin, and a c.G301A mutation in this gene has been shown to be associated with hypertrophic cardiomyopathy, which, in some instances, leads to sudden cardiac death." (PMID 38144520, 2023). "Mutations of alpha cardiac muscle 1 actin (ACTC1) had been associated with hypertrophic cardiomyopathy (HCM)." (PMID 35509884, 2022). "Variants in ACTC1 have been associated with idiopathic dilated cardiomyopathy and familial hypertrophic cardiomyopathy." (PMID 33679876, 2021). "In human studies, ACTC1 mutations have been noted in heart diseases, including dilated cardiomyopathy and hypertrophic cardiomyopathy." (PMID 33430356, 2021). "ACTC1 encodes cardiac actin and a mutation at c.G301A (p.Glu101Lys) causes hypertrophic cardiomyopathy, altered calcium sensitivity, arrhythmias, and, in some cases, sudden cardiac death." (PMID 29402189, 2018). "Mutations in the cardiac actin gene (ACTC1) are associated with the development of hypertrophic cardiomyopathy (HCM)." (PMID 29719515, 2018). "The co-occurrence of these congenital heart defects is notable because ACTC1 is well established to underlie isolated cardiac abnormalities, including dilated and hypertrophic cardiomyopathy (MIM: 613424, 612098), atrial septal defects (MIM: 612794), and left ventricular noncompaction (MIM: 613424)." (PMID 37457373, 2023). "Pathogenic heterozygous variants in the ACTC1 gene and the PLN gene have been reported to cause hypertrophic cardiomyopathy 11 [OMIM: 612098] and 18 [OMIM: 613874], respectively." (PMID 39273332, 2024). "In conclusion, WES led to the detection of two heterozygous variants in the ACTC1 gene and in the PLN gene, which represent the probable cause of hypertrophic cardiomyopathy in the patient." (PMID 39273332, 2024). "ACTC1 is known to be associated with both DCM and familial hypertrophic cardiomyopathy and is involved in cardiac muscle contraction." (PMID 29311597, 2018). "The Cardiac alpha actin 1 (Actc1) plays a role for cardiac muscle and the Y166C and M305L mutants involved in hypertrophic cardiomyopathy." (PMID 24701242, 2014). "Analysis of a more specific ontology, cardiac hypertrophy – NF-AT signaling, revealed similar genes as the general hypertrophic cardiomyopathy ontology such as Myh6, Myh7, Tnnt2, Tnni3, and Actc1." (PMID 24475304, 2014). "Further analysis, of the genes affected within the hypertrophic cardiomyopathy ontology, identified many structural genes including troponin I (Tnni3), troponin T (Tnnt2), troponin C (Tnnc1), α-actin C1 (Actc1) that are important for proper cardiac function." (PMID 24475304, 2014). "Pathogenic variants in ACTC1 have been found previously to underlie atrial septal defect, dilated cardiomyopathy, hypertrophic cardiomyopathy, and left ventricular noncompaction." (PMID 37457373, 2023). "Furthermore, some of these genes, including TNNC1, TNNT2 and ACTC1, enriched the Hypertrophic cardiomyopathy (HCM) pathway." (PMID 34069910, 2021). "The ‘Hypertrophic cardiomyopathy’ pathway was also significantly enriched, including genes such as ATPase sarcoplasmic/endoplasmic reticulum Ca2+ transporting 2 (ATP2A2) and others already identified in the PPI network (e.g., TPM1 and ACTC1)." (PMID 40559872, 2025). "Next, our KEGG analysis showed that transcripts up-regulated in the mutant cardiomyocytes were related to hypertrophic cardiomyopathy (ACTC1, MYL2, MYL3), Ca2+-dynamics regulatory pathway (ATP2B4, CACNA1C, CAMK2B, PLN), as well as cardiac-muscle contraction transcripts (ACTC1, MYH7, TNNI3, TNNT2)." (PMID 35784482, 2022).
dilated cardiomyopathy (13 papers, 2010 to 2025). Cardiomyopathy which is characterized by dilation and contractile dysfunction of the left and right ventricles. "Interacting with myosin and Z-disk’s α-actinin or intercalating disks, actin has an essential role in both force generation and force transmission, and ACTC1 gene mutations have been implicated in both hypertrophic and dilated cardiomyopathy." (PMID 39273332, 2024). "Hypertrophic and dilated cardiomyopathy causing mutations have been detected mostly in genes of sarcomere proteins such as Mybpc2, Myh7, Tnnt2, Tnnc1, Tnni3, Tpm1, Ttn, Actc1, Myl2, and Myl3." (PMID 38981849, 2024). "Mutation or downregulation of ACTC1 has been linked to dilated cardiomyopathy, the most frequent form of cardiomyopathy." (PMID 37108147, 2023). "Mutations in ACTC1 have been phenotypically related to various cardiac anomalies including dilated cardiomyopathy (DCM), restrictive cardiomyopathy (RCM), left ventricular non-compaction (LVNC), HCM, and congenital heart disease (CHD)." (PMID 36011293, 2022). "Most studies report that the ACTC1 gene was associated with dilated cardiomyopathy." (PMID 40243566, 2025). "Interestingly, in both the HIV vs. HIV+PSU and WT+PSU vs. HIV+PSU comparisons, Tnnc1, Tnnt2, and Actc1 were found to be majorly involved in the calcium signaling and dilated cardiomyopathy (DCM) signaling pathways." (PMID 37766354, 2023).
cardiac hypertrophy (8 papers, 2013 to 2025). "Several genes, including NPPA (natriuretic peptide A), ACTC1 (alpha-cardiac actin), MYL2 (myosin regulatory light chain 2), and MYL7 (myosin regulatory light chain 7), have been previously implicated in cardiac hypertrophy." (PMID 34422789, 2021). "Down-regulation of calcium handling genes (e.g., Pln, Atp2a2) and adult forms of sarcomeric genes (e.g., Actc1 and Tpm1) is another gene expression signature of cardiac hypertrophy and failure." (PMID 28861005, 2017).
atrial septal defect (7 papers, 2011 to 2023). Interauricular communication is a congenital malformation characterized by a communication between the atrial chambers of the heart. "Mutations in ACTC1 (actin alpha cardiac muscle 1) are associated with atrial septal defect, DCM, and HCM." (PMID 36357925, 2022). "Autosomal dominant mutations in ACTC1 were found in familial Atrial septal Defect and reduced expression of ACTC1 was observed in different congenital heart diseases in humans including Tetralogy of Fallot." (PMID 26252659, 2015). "Interestingly, ACTC1 mutations resulting in congenital heart defects (essentially atrial septal defects) are restricted to the first half of the protein (from residue Met84 to residue Met178)." (PMID 26061005, 2015). "Mutations in ACTC1 seem to reduce affinity of actin for myosin, and cause various CHD phenotypes such as ASD (atrial septal defect) and VSD (ventricular septal defect)." (PMID 22136190, 2011).
glioblastoma (7 papers, 2020 to 2024). The most malignant astrocytic tumor (WHO grade IV). "Among the downregulated genes, ACTC1 is an actin involved in the migration of astrocyte-derived glioblastoma cells, while TKTL1 functions in the generation of neurons." (PMID 38900784, 2024). "In vitro, the depletion of ACTC1 impedes the migratory capacity of glioblastoma cells." (PMID 38358910, 2024). "Previous studies showed that ACTC1 is related to cancer prognosis, ACTC1 expression is significantly upregulated in glioblastoma and inhibits migration of cancer cells, and ACTC1 correlates with the prognosis of glioblastoma and can be used as a novel prognostic marker in glioma." (PMID 38144520, 2023). "Thus, ACTC1, for which high expression is shown to indicate glioblastoma progression, remains a promising candidate to be investigated in a future study." (PMID 36142605, 2022). "Alpha myocardial 1 (ACTC1) was a new independent prognostic and invasive marker in glioblastoma (GBM)." (PMID 32547947, 2020). "Upregulated ACTC1 was reported in various tumors, such as head and neck cancer, bladder cancer, urothelial cancer, prostate cancer (PCa), NSCLC, BC and glioblastoma (GBM), promoting distant metastasis or multi-drug resistance." (PMID 36500393, 2022).
heart failure (7 papers, 2010 to 2024). Inability of the heart to pump blood at an adequate rate to meet tissue metabolic requirements. "However, no protein-protein interactions exist or are found between UTRN and ACTC1, which encodes the actin in cardiac cells, suggesting that progressive heart failure could be due to the failure of UTRN rescue." (PMID 20950417, 2010). "In our study, inhibition of TBX5 was shown to dysregulate several genes such as DES, NKX2-5, ACTC1, MYH6, ATP2A2 and HSPB7, which further contributed to ICM-related diseases such as failure of heart and degeneration of heart." (PMID 32423033, 2020). "In contrast, we found that overexpressed Myc bound both the promoter region and body of many cardiac-specific genes including transcription factors (Gata4, Gata6, Tbx20, Nkx2-5), structural genes (Actc1, Pln), or heart failure related genes (Nppa, Nppb), but did not induce Pol II recruitment." (PMID 27346836, 2016).
congenital heart disease (6 papers, 2013 to 2022). A heart disease that is present at birth. "ACTC1, the cardiac α-actin gene, has been reported to play roles in sporadic congenital heart disease (CHD)." (PMID 30510588, 2018). "ACTC1 plays a crucial role in early muscle development and fetal development, and reduced ACTC1 expression had an essential role in congenital heart disease and atrial septa defect." (PMID 25774290, 2015). "Actc1 is reduced in patients with congenital heart disease, while its downregulation could be responsible for cardiomyocyte apoptosis." (PMID 34395518, 2021).
Arrhythmia (5 papers, 2015 to 2021). Any cardiac rhythm other than the normal sinus rhythm. "In conclusion, we reported a novel ACTC1 gene mutation which resulted in various congenital heart defects and arrhythmia." (PMID 26061005, 2015). "TBX5-targeted genes, MYH6, ACTC1 and TPM1, were involved in arrhythmia." (PMID 32423033, 2020). "Moreover, calcium handling and contractile function genes (SLN, ACTC1, PLCD4, PLCZ), potential arrhythmia-related genes (MYO5B, KCNA5), and cytoskeleton and cellular organization-related genes (XIRP2, COL8A1, KCNA6) were among the most deregulated genes in rTOF ventricles." (PMID 26252659, 2015).
breast carcinoma (5 papers, 2020 to 2024). "To investigate the effect of ACTC1 on immune cells, we co-cultured treated breast cancer tumor cells with PBMC and selected the corresponding antibodies to detect the percentage and activity of CD8+T cells." (PMID 38358910, 2024). "Previous studies have shown that ACTC1 can promote the proliferation and migration of breast cancer cells by proteomic assay." (PMID 32547947, 2020). "This is consistent with the role of ACTC1 in GBM, colon, prostate, oral squamous cell and breast cancers." (PMID 35223984, 2021).
glioma (5 papers, 2020 to 2023). A benign or malignant brain and spinal cord tumor that arises from glial cells (astrocytes, oligodendrocytes, ependymal cells). "ACTC1 has been linked to cancer recurrence and OS rate in glioma patients, suggesting that it may be a novel independent marker for prognosis and invasion in glioma." (PMID 36131343, 2022). "In this study, KD of either ACTC1 or ACTA2 in the U251MG glioma cell line led to shorter cell motion distance." (PMID 37891844, 2023). "In this study, we initially generated U251MG glioma cells in which one of the two α-actin paralog genes, ACTC1 and ACTA2, was knocked down." (PMID 37891844, 2023). "A series of experiments have proved that ACTC1 is a marker of invasion and prognosis of glioma." (PMID 32547947, 2020). "Previously, we reported that ACTC1 KD in a malignant glioma cell line reduced cell migration, and the study results suggest that ACTA2 is also involved in glioma cell migration." (PMID 37891844, 2023). "We added U251MG glioma cells with a simultaneous KD of the ACTC1 and ACTA2 genes as “ACTC1/ACTA2-KD cells” in vitro assays to explore the significance of this complementary regulation of ACTC1 and ACTA2 expression." (PMID 37891844, 2023).